RNU6-400P (RNA, U6 small nuclear 400, pseudogene)
Gene: Small nuclear RNA gene on chromosome 12 (33,576,095 to 33,576,200, forward strand). Ensembl gene ENSG00000212475.
Homologues: Orthologues: chimpanzee U6 (94% identical), macaque U6 (85% identical), mouse Gm22969 (78% identical), guinea pig U6 (72% identical), rat LOC120093913 (65% identical), pig U6 (59% identical). Paralogues in human: RNU6-20P (82% identical), RNU6-1316P (81% identical), RNU6-434P (81% identical), RNU6-35P (80% identical), RNU6-574P (80% identical), RNU6-1091P (79% identical), RNU6-1145P (79% identical), RNU6-1323P (79% identical), RNU6-25P (79% identical), RNU6-274P (79% identical), RNU6-38P (79% identical), RNU6-45P (79% identical), and 1287 more.